GPR174 (G protein-coupled receptor 174)
Description:
G protein-coupled receptor of lysophosphatidylserine (LysoPS) that plays different roles in immune response. Plays a negative role in regulatory T-cell accumulation and homeostasis. Under inflammatory conditions where LysoPS production increases, contributes to the down-regulation of regulatory T-cell activity to favor effector response. Mediates the suppression of IL-2 production in activated T-lymphocytes leading to inhibition of growth, proliferation and differentiation of T-cells. Mechanistically, acts via G(s)- containing heterotrimeric G proteins to trigger elevated cyclic AMP levels and protein kinase A/PKA activity, which may in turn act to antagonize proximal TCR signaling. Plays an important role in the initial period of sepsis through the regulation of macrophage polarization and pro- and anti-inflammatory cytokine secretions. Upon testosterone treatment, acts as a receptor for CCL21 and subsequently triggers through G(q)-alpha and G(12)/G(13) proteins a calcium flux leading to chemotactic effects on activated B-cells. Signals via GNA13 and PKA to promote CD86 up-regulation by follicular B-cells.
Synonyms: FKSG79; GPCR17; LPS3; LYPSR3
Tractability: Small molecule: a structure with a bound ligand is known; a high-quality ligand is known; it belongs to a druggable protein family. Antibody: its Gene Ontology location is reachable by antibodies, with high confidence; UniProt places it where antibodies can reach, with medium confidence; UniProt predicts a signal peptide or a membrane-spanning region. PROTAC: ubiquitination databases record sites on it; a small molecule that binds it is known.
Target class: Family A G protein-coupled receptor; Membrane receptor
Gene: Protein-coding gene on chromosome X (79,144,678 to 79,175,318, forward strand). Ensembl gene ENSG00000147138.
Subcellular location: Cell membrane
Subcellular location (Human Protein Atlas): Plasma membrane; Centriolar satellite; Vesicles
Gene Ontology:
Molecular function: G protein-coupled receptor activity; protein binding; bioactive lipid receptor activity
Biological process: negative regulation of interleukin-2 production; G protein-coupled receptor signaling pathway
Cellular component: plasma membrane; membrane
Homologues: Orthologues: chimpanzee GPR174 (99% identical), macaque GPR174 (98% identical), rabbit GPR174 (94% identical), pig GPR174 (92% identical), dog GPR174 (92% identical), guinea pig GPR174 (89% identical), mouse Gpr174 (88% identical), rat Gpr174 (88% identical). Paralogues in human: RXFP3 (25% identical), GPR183 (22% identical), GPR132 (22% identical), P2RY11 (18% identical), GPR151 (15% identical), GPR141 (15% identical), GPR146 (13% identical).